SMAD4 (SMAD family member 4)
Diseases named in the same sentence as SMAD4 in open-access papers (continued):
Sharing a sentence is not in itself a finding about the gene and the disease.
breast carcinoma (continued). "We therefore examined how the complexes of Smad4 and R-Smads mediate estrogen signal transduction through their interactions with ERα in breast cancer cells." (PMID 19943940, 2009). "To further investigate the significance of Smad4 expression in breast cancer, we examined the specimen with both benign ductal epithelial and cancer cells." (PMID 19943940, 2009). "It is likely that in an ERα-positive breast carcinoma with aberrant expression of Smad4, TGF-β not only is unable to inhibit tumor growth, but also promote tumor progression through enhancing the estrogen-ERα mediated cell proliferation." (PMID 19943940, 2009). "Smad4 expression was investigated by immunohistochemistry in formalin-fixed, paraffin-embedded tissue from 197 samples of primary breast cancer obtained between 1986 and 1998." (PMID 16438724, 2006). "According to the suggested role of Smad4 as a tumor suppressor we observed that expression of Smad4 is lower in human breast cancer than in surrounding breast epithelium." (PMID 16438724, 2006). "Overall Smad4-expression was significantly lower in breast carcinoma (median IRS: 3) than in normal breast epithelia (median IRS: 8, p < 0.001, n = 50, sign test)." (PMID 16438724, 2006). "Since tumors often display altered TGF-β signaling, particularly involving the Smad-pathway, we investigated the role of Smad4-expression in breast cancer." (PMID 16438724, 2006). "Immunohistochemistry revealed both cytoplasmic and nuclear staining for Smad4 in both normal breast epithelia and breast carcinomas." (PMID 16438724, 2006). "Smad4 expression in tumor tissues was compared to that of surrounding normal tissues and correlated to established prognostic markers for breast cancer as well as overall survival." (PMID 16438724, 2006). "We have used immunohistochemical staining to show that Smad4 expression is markedly decreased in breast cancer compared to surrounding normal breast epithelium." (PMID 16438724, 2006). "In order to gain further insight into the status of Smad signal transduction in breast cancer progression, we used immunohistochemistry to analyze the expression of Smad4 in archival tissues of 197 breast cancer patients." (PMID 16438724, 2006). "This study aimed to elucidate the molecular mechanisms through which the TET1/SMAD4/GATA6 regulatory axis governs CAF activation in breast cancer, focusing on its role in sustaining TGF-β signaling, promoting stromal-tumor crosstalk, and driving tumor progression." (PMID 40216762, 2025). "Using a highly metastatic variant of the triple-negative MDA-MB-231 human breast cancer line, MDA-MB-231-HM (231-HM), we reduced SMAD4 expression using two short-hairpin RNAs (shRNAs), SMAD4sh4 and SMAD4sh5, that target different regions of the SMAD4 gene." (PMID 38689334, 2024). "Gene signature upregulated by BMP4 in the absence of SMAD4 was associated with poor prognosis in breast cancer patients, whereas gene signature upregulated by BMP4 in the presence of SMAD4 was associated with improved prognosis." (PMID 38689334, 2024). "SMAD3 and SMAD5 were overexpressed in all types of breast cancer, which could be related to the reduced expression of miR-145, and the findings for SMAD4 and miR-155 were similar." (PMID 39337574, 2024). "Next, we explored the link between SMAD4 and breast cancer progression." (PMID 39118232, 2024). "ATF3 promotes colon cancer metastasis and is described to build a stable complex with Smad4 that could be responsible for the activation of genes that participate in TGF-β1-mediated breast cancer progression." (PMID 38658567, 2024). "Consequently, our findings implied that SMAD4 promoted the breast cancer migration and invasion through IBSP." (PMID 39118232, 2024). "In addition, SMAD3, SMAD6, and SMAD7 were lowly expressed in stage II breast cancer, while SMAD4 and SMAD2 were lowly expressed in stage III cancer." (PMID 38514720, 2024).
breast carcinoma (continued). "Detailed researches discovered that dyslipidemia interaction with USP9x and SMAD4 might govern TGF-β signaling during breast cancer metastasis." (PMID 39135158, 2024). "The results showed that five lncRNAs including HOTAIR, DANCR, PVT1, LINC00511, and NEAT1 and 16 miRNAs and five of their targets—VEGFA, BTG2, E2F3, IRAK1, and SMAD4—have significantly different expression patterns in normal individuals compared to those with breast cancer." (PMID 36726376, 2023). "According to Liu and colleagues, SMAD4 may play a role in the progression of breast cancer and be used as a prognostic indicator for the disease." (PMID 36726376, 2023). "SMAD4 expression was lower in breast cancer tissue than in the surrounding breast epithelium." (PMID 34746770, 2021). "For example, hsa_circ_0061825 could promote breast cancer progression, circ_SMAD4 contributes to gastric carcinogenesis, and circRNA-002178 acts as the tumor promoter in lung adenocarcinoma." (PMID 34568326, 2021). "Methylation status for PTEN and SMAD4 were statistically significant as breast cancer patients reported hypermethylation compared to benign and control groups (77.1 ± 17.9 vs. 24.9 ± 4.5 and 15.1 ± 1.4 and 70.1 ± 14.4 vs. 28.2 ± 0.61 and 29.5 ± 3.6, respectively)." (PMID 33825073, 2021). "Finally, the competition between TGFβ and BMP7 (bone morphogenetic protein-7) for the common signal transducer SMAD4 has pointed out the latter as a promising drug target in breast cancer treatment." (PMID 33498521, 2021). "Evidence suggests that the down-regulation of SMAD4 reduces metastasis in breast cancer cells." (PMID 31487369, 2020). "A total of 1180 miRNA–mRNA matched samples of breast cancer (including 1176 cancer and 104 normal tissues) were collected from the TCGA and the expression levels of crucial DEMs (miR-1255a and miR-455) and their target genes (SMAD4 and CDKN1B) were calculated." (PMID 31763681, 2020). "TGF-β/Smad signaling plays an important role in the progression of EMT in breast cancer, in which phosphorylation of Smad2 triggers the formation of a complex between Smad2 and Smad4, resulting in nuclear translocation of the Smad2/Smad4 complex and subsequent gene transcription." (PMID 32226772, 2020). "However, OLA1 and TGF β 1, SMAD3 SMAD4 has a strong positive correlation in the breast cancer tissue of the TCGA database (right)." (PMID 32528278, 2020). "More importantly, we predicted miR-1255a may regulate the expression of SMAD4 in breast cancer cells." (PMID 31763681, 2020). "For example, Osthole, showed to inhibit collagen I and III expressions in TGF-β1 treated mouse cardiac fibroblasts (CFs) by modulating Smad4 expression and Bergapten was reported to deplete estrogen receptor in breast cancer cells in respond to TGF β 1 by regulating Smad4 expression." (PMID 31277646, 2019). "However, some studies argue that SIRT1 suppresses cancer cell migration and invasion, such as, by targeting ARHGAP5 in gastric cancer, by inhibiting the TGF-β/Smad4/MMP-7 axis in breast cancer and by regulating autophagy in CRC." (PMID 31068761, 2019). "Furthermore, the TGFβ signalling pathway, which has major roles in the EMT, is suppressed by Dach1 via binding to Smad4 in breast cancer tissue, thereby controlling the EMT." (PMID 31405829, 2019). "While the inactivating mutations in Smad2 and Smad3 have not been reported in breast cancer, this has been reported in Smad4." (PMID 31798766, 2019). "Our study aims to define the prognostic significance of TGFβ1, SMAD4 and TIF1γ expression in breast cancer patients and to detect possible interactions among those markers that might affect the outcome." (PMID 26040677, 2015).
breast carcinoma (continued). "Besides, the prognostic significance of the TGFβ1, SMAD4 in breast cancer patients is an area of many contradictions." (PMID 26040677, 2015). "This may be concordant with some studies that tested the effect of SMAD4 expression in operable breast cancer." (PMID 26040677, 2015). "Among them, HDAC4-mediated deacetylation of the SMAD4 promoter may lead to 5-FU resistance in breast cancer cells." (PMID 26044366, 2015). "Similarly, SMAD4 shifts from its tumor suppressor role to an aggressiveness factor in a mouse model of breast cancer by promoting bone metastasis through TGF-β-activated expression of IL-11." (PMID 24708576, 2014). "Subsequently, many studies have shown that Smad4 is underexpressed in various human tumors, including stomach cancer, squamous cell carcinoma of the esophagus, and breast cancer, and Smad4 has been proposed as a prognostic marker for tumor formation and progression." (PMID 24636138, 2014). "Increasing SMAD4 germline expression is unlikely to predispose to breast cancer due to its important role as a tumor suppressor suggesting that SMAD4 is not involved in susceptibility." (PMID 21835029, 2011). "While SMAD4 is not preferentially mutated in breast cancer, rarely occurring variants, such as c.1350G > A, probably serve as low to medium penetrating inherited germline mutations with prognostic value." (PMID 21835029, 2011). "In breast carcinoma cells that lack one component of the Smad3/4 complex, Smad3 or Smad4 may act as a coactivator or corepressor for ERα that confers a TGF-β activating or suppressing signal on the estrogen signaling pathway." (PMID 19943940, 2009). "In addition, we found that the expression of Smad4 was downregulated with increased cytoplasmic localization in ERα-positive human infiltrating breast cancer tissue." (PMID 19943940, 2009). "The mechanism for dysregulation of Smad4 expression in ERα-positive infiltrating breast cancer is still unknown." (PMID 19943940, 2009). "However, little is known about the expression level of Smad4 or its prognostic significance in breast cancer." (PMID 16438724, 2006). "Although the expression of Smad4 in breast cancer tissues as well as in normal epithelia varied greatly between specimens from individual patients, Smad4 expression was significantly reduced in tumor tissues as compared to the surrounding normal epithelia within the same specimen." (PMID 16438724, 2006). "However, our observation in a comparative dataset on two other breast cancer lines suggests that BMP-induced regulation of β-CATENIN may require the contribution of additional factors other than SMAD4 and thus occurs in a cell-dependent manner." (PMID 38731813, 2024). "Together, these findings indicate that a subset of breast cancer patients with low Smad4 expression might not be susceptible to the known EMT-reversing effects of eribulin, due to upregulation of the EMT-promoting transcription factor Slug." (PMID 31481735, 2019). "Consequently, we hypothesise that high Smad4 expression could serve as a potential biomarker of the ability of eribulin to reverse EMT in breast cancer patients." (PMID 31481735, 2019). "Moreover, SMAD4 is sensitive to lapatinib according to the COSMIC database with no mutational signature in breast cancer cell-lines." (PMID 28288164, 2017). "Thus, it is plausible to speculate that SIRT1 might regulate SMAD4 and breast cancer metastasis in a SIRT7 deacetylase-dependent manner." (PMID 28827661, 2017). "Presently, it is not known whether SMAD3 and SMAD4 germline alterations are involved in breast cancer predisposition." (PMID 21835029, 2011).
breast carcinoma (continued). "In addition, the expression of Smad4 are decreased and largely restricted in the cytoplasm of some of ERα-positive infiltrating human breast cancer cells in contrast to the benign breast tissue in which Smad4 was strongly expressed in both cytoplasm and nucleus of ductal epithelial cells." (PMID 19943940, 2009). "Our data show that Smad4 expression in breast cancer is lower than in normal adjacent breast epithelial tissue and imply that impairment of TGF-β/Smad-signaling because of loss of TβRII or Smad4 might improve 5-year survival by possibly slowing down metastases." (PMID 16438724, 2006). "This study aimed to investigate the clinical role of SMAD4 and AKR1B1 methylation as noninvasive prognostic biomarkers in breast cancer." (PMID 41760667, 2026). "In breast cancer cohorts (TCGA, METABRIC; n = 1,986), TET1 expression positively correlated with genes in the SMAD/TGF-β pathway, particularly SMAD4 (P < 0.05)." (PMID 40216762, 2025). "Here, we identified the TET1/SMAD4/GATA6 regulatory axis as a central mechanism governing CAF transformation and function in breast cancer." (PMID 40216762, 2025). "Several genes found on chromosome 18, such as SMAD4, SMAD2, MIB1, and MBD1, are involved in breast cancer development and progression." (PMID 38803515, 2024). "The analysis showed a significant increase in the concentration of SMAD3, SMAD4, and SMAD5 in all types of breast cancer samples compared to the control." (PMID 39337574, 2024). "Knockdown of Smad4 effectively inhibits TGF-β-induced EMT in normal mammary cells and strongly suppresses bone metastasis of breast cancer cells in nude mice." (PMID 38818471, 2024). "We observed in the TCGA portal that SMAD4 was decreased in colon adenocarcinoma (COAD, upper) and breast cancer (BRCA, lower) samples compared to normal samples." (PMID 39113194, 2024). "SMAD4, SMAD2, SMAD3, SMAD7, SMAD1, SMAD6, and SMAD5 showed genetic variation in 1.8%, 1.2%, 1.1%, 0.8%, 0.7%, 0.6%, and 0.5% of patients with breast cancer, respectively." (PMID 38514720, 2024). "For example, lncRNA LITATS1 inhibits EMT in breast cancer and non-small cell lung cancer cells by promoting polyubiquitination and proteasomal degradation of TβRI 164; lncRNA LINP1 inhibits TGF-β1/Smad4-induced EMT and cell invasion in lung cancer cells." (PMID 38818471, 2024). "Our results are consistent with previous reports that SIRT1 suppresses EMT in cancer by deacetylating Smad4 and inhibiting TGF‐β signaling in breast cancer and oral squamous cell carcinoma." (PMID 37667739, 2023). "SMAD4 mRNA levels correlate with the expression of some DDR genes, pointing to a possible signature role for SMAD4 similar to BRCA1 in breast cancer." (PMID 35144669, 2022). "In breast cancer, tumor cells often secrete excess TGF-β protein, forming Smad3/Smad4 complexes in the nucleus, which increases the expression of SLUG protein and promotes tumor invasion, and knockdown of Smad3 protein reduces tumor invasion and metastasis." (PMID 35251569, 2022). "In BT-549 and MDA-MB-231 breast cancer cells, SIRT7 deacetylated and destabilized SMAD4, resulting in reduced formation of the SMAD2/SMAD3-SMAD4 complex." (PMID 36291902, 2022). "GSLs were shown to be involved in the TGF-β-induced EMT process in normal murine mammary gland NMuMG and human mammary carcinoma MCF7 cells, both of which express SMAD4." (PMID 35151689, 2022). "SMAD4, of which targets are enriched in FIR20 cells, is essential to inhibit ESR1 transcription in breast cancer cell lines." (PMID 35579852, 2022). "In breast cancer cells, GATA3 inhibits Smad4-mediated FSCN1 overexpression by suppressing the binding of Smad4 to the FSCN1 promoter." (PMID 33614909, 2021). "As tumor suppressor factors, TGFβRII or SMAD4 knockout significantly accelerated progression of malignant tumors; examples include APC inactivation in intestinal polyps, PyMT-induced breast cancer, and pancreatic injury induced by Kras." (PMID 34095135, 2021).
breast carcinoma (continued). "Smad4 gene that has interaction with estrogen receptor α is required for TGF-β-induced epithelial to mesenchymal transition and bone metastasis of breast cancer cells." (PMID 33800915, 2021). "In models of breast cancer metastases and kidney fibrosis, SIRT1 suppressed EMT by deacetylating Smad4 and thus, repressing TGFβ-induced MMP7." (PMID 33946753, 2021). "Accumulating evidence has proved that SMAD4 is a key downstream effector of transforming growth factor-β (TGF-β) signaling pathway, which is known to reduce breast cancer cell invasion and tumor-induced angiogenesis." (PMID 31763681, 2020). "SMAD4 WT and T63V mutants were cloned into the retroviral vector pMSCV-FLAG, followed by viral infection with MDA-MB-468, a SMAD4-null breast cancer cell line." (PMID 33199824, 2020). "FHL1 induced the expression of tumor suppressor genes by increasing the nuclear translocation of Smad4 in hepatocellular carcinoma cells and inhibiting the phosphorylation of AKT in human breast cancer cells." (PMID 33322515, 2020). "In SMAD4-null human breast carcinoma MDA-MB-468 cells, NUAK2 protein expression and weak inducibility by TGFβ were rescued upon reconstitution of SMAD4 in the cells." (PMID 30622137, 2019). "Accumulating evidence suggests that Smad4 is required for TGF-β downstream genes, including CTGF and IL-11, which are involved in BM in breast cancer." (PMID 31349837, 2019). "Further studies indicated that TGF-β can have direct pro-oncogenic effects on tumor cells by stimulating their invasion and metastasis, and Smad4 is required for the TGF-β-induced EMT and bone metastasis of breast cancer cells." (PMID 29955155, 2018). "Altogether, Smad4 plays an important role in TGF-β-induced CSC formation and cancer progression in breast cancer." (PMID 29955155, 2018). "To further confirm the potential desumoylation function of SENP2 on Smad4, we created SENP2 knockdown MDA-MB-231 breast cancer cell line (MDA-MB-231-2B) by CRISPR-Cas9 approach (lanes 1-2 and S1D)." (PMID 29955155, 2018). "It has been reported that Smad4 is required for TGF-β-induced EMT and bone metastasis of breast cancer cells." (PMID 29955155, 2018). "Previous results have demonstrated that SMAD3 and SMAD4 are critical for TGF-β-induced EMT and the metastasis of breast cancer cells." (PMID 25970785, 2015). "In breast cancer cells, SMAD4 is required for TGF-β-induced uPA, whereas exogenous expression of SMAD4 in colon cancer cells reduces uPA production." (PMID 23984088, 2013). "At least four well-known breast cancer genes including SMAD2, SMAD4, TGFB3 and TGFBR3 are involved in palate development." (PMID 23281707, 2012). "To confirm this observation, we performed a similar experiment in the breast cancer cell line MDA-MB-468 which lacks endogenous ERα and Smad4." (PMID 19943940, 2009). "Our findings suggest that Smad4 is required for TGF-β to inhibit ERα-induced transcription, which provides important information regarding TGF-β resistance in breast cancer cells." (PMID 19943940, 2009). "Western Blot analysis of breast cancer cells of increasing malignancy (MCF10A, MCF10At1k.cl2, MCF10CA1h, MCF10CA1a) showed that Smad4 expression decreased with increasing malignancy of the tumor cell line." (PMID 16438724, 2006). "In conclusion, SMAD4 and AKR1B1 methylation may serve as significant epigenetic markers affecting breast cancer prognosis, potentially indicating more aggressive disease and poorer outcomes in these patients." (PMID 41760667, 2026). "Our findings unveil a mechanism whereby endocrine therapy-induced SMAD4 downregulation drives acquired resistance by integrating ER and ERBB signaling and suggest a rational treatment strategy for endocrine-resistant HR + HER2− breast cancer patients." (PMID 38914552, 2024).